MIR124-1 (microRNA 124-1)
Synonyms: hsa-mir-124a-1; hsa-mir-124-1; MIR124A; MIR124A1; MIRN124-1; MIRN124A1; mir-124-1
Gene: MicroRNA gene on chromosome 8 (9,903,388 to 9,903,472, reverse strand). Ensembl gene ENSG00000284321.
Gene Ontology:
Biological process: miRNA-mediated post-transcriptional gene silencing
Cellular component: RISC complex
Homologues: Orthologues: chimpanzee MIR124-1 (100% identical), dog MIR124-1 (100% identical), guinea pig MIR124-1 (100% identical), macaque mml-mir-124a-2 (100% identical), mouse Mir124a-1 (100% identical), pig ssc-mir-124a-2 (100% identical), rabbit MIR124-1 (100% identical), rat Mir124-1 (100% identical). Paralogues in human: MIR124-2 (85% identical), MIR124-3 (84% identical).
Diseases named in the same sentence as MIR124-1 in open-access papers:
MIR124-1 is named in the same sentence as 2 diseases in open-access papers, as found by Europe PMC text mining. Sharing a sentence is not in itself a finding about the gene and the disease.
MIR124-1 shares sentences with these, for which no sentence is quoted: gastric cancer (2 papers); tumor (1).